ALB (albumin)
Diseases named in the same sentence as ALB in open-access papers (continued):
Sharing a sentence is not in itself a finding about the gene and the disease.
Hypoalbuminemia (continued). "The risk of postoperative complications in patients with preoperative hypoalbuminemia (serum albumin < 35 g/L) was 1.89 times higher than in those with normal preoperative albumin (preoperative serum albumin ≥ 35 g/L)." (PMID 37805523, 2023). "Albumin is produced in the liver, and hypoalbuminemia is a common complication in patients with cirrhosis and can lead to ascites or edema, leading to increased mortality." (PMID 38007536, 2023). "Serum albumin is often used to assess nutritional status and systemic inflammation, and studies have shown that patients with hypoalbuminemia tend to have more severe bronchiectasis." (PMID 36742422, 2023). "In septic patients, human albumin solution can be given for two indications: to restore or expand intravascular volume and to supplement serum albumin in the septic patients with hypoalbuminemia." (PMID 37374251, 2023). "Noh and coworkers recently published a retrospective study analyzing the prognostic value of serum albumin level and the possible mechanisms linking hypoalbuminemia at the time of hospitalization with mortality in patients poisoned with organophosphates." (PMID 37047631, 2023). "Relationships between sarcopenia as indicated by the psoas muscle mass index and hypoalbuminemia (albumin ≤ 3.5 g/dL) with overall survival (OS) and metastasis-free survival (MFS) were determined." (PMID 37371699, 2023). "The patients with normal albumin levels were more likely to be male than those with hypoalbuminemia (70.5% vs. 57.8%; P < 0.001)." (PMID 37277756, 2023). "The incidence of hypoalbuminemia events varied based on the level of albumin measured at different stages of hospitalization." (PMID 37919691, 2023). "Given the pervasiveness of hypoalbuminemia in this study cohort, we aimed to use albumin treatment for improving the outcomes of ARDS patients." (PMID 37089426, 2023). "Many studies have reported that serum albumin level is a nutritional indicator for HD, and previous studies using long-term clinical data have demonstrated a relationship between hypoalbuminemia and mortality in patients on HD." (PMID 37095523, 2023). "Human albumin solutions, including hypo-oncotic (4%), iso-oncotic (5%), and hyper-oncotic (20–25%) formulations, are used to counteract hypoalbuminemia or for volume replacement." (PMID 36768655, 2023). "There is a clear correlation between albumin serum concentration and morbidity rates, however, the question remains if albumin replacement improves outcomes or if hypoalbuminemia is just a marker for severity of illness." (PMID 37218881, 2023). "The review emphasizes the importance of conducting trials to assess the effectiveness of albumin in correcting hypoalbuminemia in sepsis, its impact on patient outcomes, and the establishment of appropriate dosing and administration methods." (PMID 38139434, 2023). "Hypoalbuminemia (albumin less than 3.5 g/dl) was noted in 40% of the study population; 8% of subjects had missing data regarding albumin at diagnosis." (PMID 36965007, 2023). "In Western countries, low albumin levels (i.e., hypoalbuminemia) can occur in patients with depression who develop drug resistance." (PMID 37340352, 2023). "T2DM can lead to decreased serum albumin levels, and insulin is clinically needed to prevent hypoalbuminemia." (PMID 36747238, 2023). "Hypoalbuminemia usually happens due to albumin distribution volume augmentation and increased capillary permeability with secondary escape of serum albumin into the interstitial space." (PMID 37959235, 2023). "In Western countries, low albumin levels or hypoalbuminemia coexist as drug resistance develops in patients with depression." (PMID 37340352, 2023). "Recent studies have demonstrated that ALB is closely correlated with inflammation, and hypoalbuminemia was frequently seen in patients with inflammatory diseases." (PMID 36908271, 2023).
Hypoalbuminemia (continued). "Despite the strong association between hypoalbuminemia and AKI, a limited number of studies have evaluated the influence of serum albumin levels before surgery on AKI following surgery in patients who received aortic surgery for ATAAD." (PMID 36836115, 2023). "Albumin can improve the function of the respiratory, cardiovascular, and central nervous systems in critically ill patients with hypoalbuminemia." (PMID 38020714, 2023). "Although the first-born child had heavy proteinuria and hypoalbuminemia and needed daily albumin replacement to manage severe edema, the second had only mild proteinuria after birth." (PMID 37101999, 2023). "The risk of hypoglycemia during hemodialysis in the patients with hypoalbuminemia (serum albumin<35 g/L) was 13.963 times than that of the patients with normal-level serum albumin." (PMID 37833779, 2023). "Due to many COVID‐19 patients developing hypoalbuminemia at admission, we further analyzed the correlation between gut microbes and albumin." (PMID 38149007, 2023). "Hypoalbuminemia, defined as a serum albumin concentration below 3.5 g/dL, is commonly detected in hospitalized adult patients, being reported with a prevalence higher than 70% in the elderly." (PMID 37762957, 2023). "And using enteral caloric implementation, hypoalbuminemia improved slightly after 1 month, and serum albumin returned to normal after 12 months." (PMID 37125379, 2023). "Compared to those with albumin levels ≥ 35 g/L, the cumulative mortality for participants with hypoalbuminemia combined with single CMD and multiple CMDs were noticeably higher." (PMID 37957767, 2023). "CRS (OR = 13.618; 95% CI = 1.499–123.709; P = 0.013) and baseline albumin (ALB) (OR = 0.854; 95% CI = 0.754–0.967; P = 0.020) were identified as the independent clinical factors associated with post-CAR-T hypoalbuminemia." (PMID 37919691, 2023). "Measures to increase albumin concentration as well as replacement of albumin function have to be initiated in patients with severe hypoalbuminemia." (PMID 37342623, 2023). "Albumin is commonly administered in patients receiving red blood cell (RBC) transfusion during major abdominal surgery to correct hypoalbuminemia and volume depletion." (PMID 36768655, 2023). "The median serum albumin level was 3.9 g/dL (2.1–4.7 g/dL), and patients with hypoalbuminemia accounted for 67.7%." (PMID 37945672, 2023). "Because around 97% of MPA binds to albumin, hypoalbuminemia increases the free fraction of MPA, resulting in faster clearance of and thereby reduced exposure to MPA." (PMID 36624529, 2023). "Serum albumin levels were measured upon admission, and hypoalbuminemia was defined as a total albumin level < 35 g/L." (PMID 37838687, 2023). "Addressing the first point, liver cirrhosis can result in impaired hepatic ALB synthesis, although hypoalbuminemia is clinically evident only in the presence of chronic and severe hepatic insufficiency." (PMID 37762957, 2023). "We demonstrate that higher serum-albumin levels are a patient-specific predictor for faster recovery from nephrotic range proteinuria or hypoalbuminemia." (PMID 37563703, 2023). "In cirrhosis, where the benefits of albumin are clearer, the role of fluid choice, including hyper-oncotic albumin for small-volume resuscitation and hypoalbuminemia correction, is important." (PMID 38139434, 2023). "A study has reported that serum albumin levels can independently predict pneumonia in acute ischemic stroke patients, and early hypoalbuminemia is an independent factor for pneumonia and sepsis in ICH patients." (PMID 37388726, 2023). "The importance of disease severity and hypoalbuminemia in tailoring albumin therapy is also addressed, emphasizing the need for context-specific prescribing." (PMID 38139434, 2023). "Clinical trials are necessary to clarify the role of albumin in sepsis, evaluate its effectiveness in correcting hypoalbuminemia, assess patient outcomes, and determine the optimal dosages and protocols." (PMID 38139434, 2023).
Hypoalbuminemia (continued). "We also observed that of the 41 patients with HRS, 95.1% (n=39) had hypoalbuminemia (mean value=2.20 g/dL), whereas 4.9% (n=2) had normal serum albumin levels." (PMID 38034151, 2023). "Hypoalbuminemia (serum albumin < 35 g/L) is commonly seen in ICU settings in up to 76% of critically ill children and up to 82% in certain critically ill adults." (PMID 37888650, 2023). "Inflammation augments capillary permeability, leading to the expansion of the interstitial space and amplification of the distribution volume of albumin, resulting in hypoalbuminemia due to the inflammatory state." (PMID 37653556, 2023). "Hypoalbuminemia is a prevalent comorbidity in cachexia, and albumin levels have shown to explain PK variability in PopPK analyses of the majority of molecules in GC treatment." (PMID 36631818, 2023). "Hypoalbuminemia with hyperglobulinemia which also altered the albumin to globulin (A:G) ratio was noticed in 61% (n = 14) and 87% (n = 20) samples, respectively." (PMID 36985312, 2023). "According to the baseline albumin value, the mean duration of PD for the group with hypoalbuminemia was determined to be 30 months, and the group with normal albumin level was determined to be 35 months." (PMID 36762995, 2023). "Hypoalbuminemia is known as a predictor of mortality by itself, and the albumin level in acute conditions, including sepsis, decreases in response to various inflammatory effects." (PMID 36832250, 2023). "Of 1002 participants included in the analysis, the mean level of albumin was 38.5 g/L (± standard deviation, 4.0 g/L), and 174 (17.4%) had hypoalbuminemia (albumin < 35 g/L)." (PMID 37957767, 2023). "Albumin is a strong predictor of death in many conditions, and hypoalbuminemia is common in elderly individuals." (PMID 37276211, 2023). "The mechanism underlying the association between hypoalbuminemia and CMS-induced kidney injury is complex and multifactorial, with the different physiological functions of albumin likely playing a significant role." (PMID 37508279, 2023). "Decreased serum albumin levels are common in COVID-19 patients, and previous studies have shown that hypoalbuminemia is correlated with increased mortality." (PMID 36788868, 2023). "According to the nadir of serum albumin, hypoalbuminemia occurred most frequently in patients with severe CRS (78.57%)." (PMID 37919691, 2023). "The incidence of hypoalbuminemia was lowest at admission (12.68%) and was highest at the nadir of serum albumin (45.07%)." (PMID 37919691, 2023). "Because of persistent hypoalbuminemia, he was started on intravenous albumin at a dose of 10 g every 10 days, while for persistent proteinuria, he was started on Angiotensin Converting Enzyme Inhibitor." (PMID 38136965, 2023). "Hyperglobulinaemia is often reported in FIP and can be accompanied by hypoalbuminaemia or low-to-normal serum albumin." (PMID 37766254, 2023). "While the mechanism behind hypoalbuminemia in COVID-19 is likely multifactorial and low albumin levels were seen predominately in adults with severe COVID-19 suggesting a phenomenon beyond hepatocellular dysfunction." (PMID 37744432, 2023). "The clinical definition of adult nephrotic syndrome includes massive proteinuria (≥3.5 g/day), hypoalbuminemia (serum albumin ≤ 3.0 g/dL), edema and dyslipidemia (hyper-LDL cholesterol)." (PMID 37241051, 2023). "We aimed to identify the impact of serum albumin on the prognosis of SAP and the association between albumin infusions and mortality for hypoalbuminemia patients." (PMID 37277756, 2023). "Addressing hypoalbuminemia in sepsis is crucial, given the promising results in cirrhosis with higher on-treatment serum albumin levels." (PMID 38139434, 2023). "Hypoalbuminemia (albumin level below 35 g/L) was found in 85% of the patients; serum sodium levels below 135 mmol/L were found in 82.5%; and thrombocytopenia (platelets less than 150 x 109/L) was reported in 37.5% of the patients." (PMID 37038378, 2023).
Hypoalbuminemia (continued). "Regarding albumin levels, most end-stage renal disease patients suffer from hypoalbuminemia for several reasons, such as a low protein diet, protein loss through urine, and dialysate, especially with high flux filters." (PMID 38107705, 2023). "Human serum albumin treatments are mainly used for hypoalbuminemia correction and fluid resuscitation in critically ill patients, such as those with sepsis and liver cirrhosis patients." (PMID 37277756, 2023). "The high levels of free radicals were determined through the nitroxide radical TEMPOL, which probably led to increased oxidation of HSA and hypoalbuminemia in severe COVID-19." (PMID 36982882, 2023). "When the patients with hypoalbuminemia at baseline, first year, and mean albumin groups were compared, it was found that patients with hypoalbuminemia at baseline had a longer duration of peritoneal dialysis." (PMID 36762995, 2023). "Given the common occurrence of hypoalbuminemia in older adults, serum levels of albumin and calcium will be used to adjust the calcium value (corrected calcium value = Ca + 0.8 [40 − albumin])." (PMID 38202104, 2023). "Hypoalbuminemia is defined as a serum concentration of albumin < 3.5 g/dL and is a common condition in more than 50% of elderly patients affected by a hip fracture." (PMID 37445579, 2023). "It emphasizes identifying sepsis patient subgroups that are most likely to benefit from albumin therapy, particularly exploring the correction of hypoalbuminemia." (PMID 38139434, 2023). "Nephrotic syndrome (NS) is defined by the presence of (i) severe proteinuria (≥40 mg/m2/h or a urine protein/creatinine ratio of ≥200 mg/g or 3+ proteins on urine dipstick), (ii) hypoalbuminemia (albumin < 2.5 g/dL), and (iii) edema." (PMID 38136965, 2023). "The probability of a poor prognosis was 70% in patients with hypoalbuminemia, compared to 24% in patients with normal albumin levels." (PMID 38226092, 2023). "Human albumin solutions, including hypo-/iso-oncotic (4–5%) or hyper-oncotic (20–25%) formulations, are administered to correct hypoalbuminemia and expand intravascular volumes." (PMID 36768655, 2023). "Many inflammatory and infectious diseases, traumatic injuries, and multiorgan failure are characterized by low levels of serum albumin, with more and more studies reporting hypoalbuminemia in patients with COVID-19." (PMID 36982882, 2023). "In patients with critical illness, hypoalbuminemia is often observed due to changes in albumin kinetics related to capillary leakage, metabolism, and oxidative modifications of albumin molecules." (PMID 37762860, 2023). "Albumin was divided into normal and hypoalbuminemia, and hypoalbuminemia was classified into three levels: mild, moderate, and severe." (PMID 37206105, 2023). "Most patients showed hypoalbuminemia with decreased levels of total protein, albumin and prealbumin (7, 7 and 8 cases, respectively)." (PMID 37552996, 2023). "Hypoalbuminemia is frequently observed in patients with advanced cirrhosis and is generally defined as an intravascular albumin level < 3.5 g/dL." (PMID 37432160, 2023). "According to the nadir of serum albumin, hypoalbuminemia occurred most frequently in patients with severe CRS (78.57%), the incidence of which was slightly lower at 56.52% in the mild CRS group." (PMID 37919691, 2023). "Hypoalbuminemia (serum albumin < 35 g/L) is more prevalent among elderly patients with preoperative hip fractures and has been strongly associated with various postoperative complications and early mortality." (PMID 37838687, 2023). "Propensity score matching (PSM) analysis was adopted to evaluate the effect of albumin infusion for hypoalbuminemia patients with SAP." (PMID 37277756, 2023). "Serum albumin reflected the patient's nutritional status, and hypoalbuminemia severely impaired the healing ability of the anastomotic site due to decreased collagen synthesis." (PMID 36718787, 2023).
Hypoalbuminemia (continued). "The patients were divided into two groups according to the level of ALB, namely the normal group (ALB ≥ 35 g/L, n = 344) and hypoalbuminemia group (ALB < 35 g/L, n = 216)." (PMID 37875880, 2023). "In serum samples from patients with COVID-19, 3-Maleimido-PROXYL was characterized by low immobilization, which was probably due to the low concentration of reduced HSA and hypoalbuminemia (serum albumin levels < 3.5 g/dL)." (PMID 36982882, 2023). "MST was significantly shorter for cats with anemia (89 vs. 356 days; P = 0.014), thrombocytopenia (22 vs. 156 days; P = 0.004), hypoalbuminemia (78 vs. 367 days; P = 0.033) and low albumin‐to‐globulin ratio (<0.2) (67 vs. 322 days; P = 0.024)." (PMID 38053473, 2023). "Hypoalbuminemia occurs in dogs, horses, and humans envenomed by Dp, possibly due to albumin leakage and extravasation secondary to vasculitis and capillary damage, especially at the envenomation site." (PMID 37888640, 2023). "Serum albumin level of 30 g/l has often been considered as the threshold for hypoalbuminemia and the treatment target in clinical trials that aimed to investigate the effect of albumin administration on the prognosis of critically ill patients." (PMID 35769376, 2022). "For adults with low albumin levels or hypoalbuminemia, especially those with chronic diseases, the sleep timing should be adjusted to ensure the optimal sleep duration." (PMID 35655296, 2022). "Initial laboratory results showed leukocytosis (WBC 20 K/microliter), significant thrombocytosis elevated inflammatory markers (CRP 9 mg/dL, ESR 85 mm/h), and mild hypoalbuminemia (albumin 3 g/dl); all muscle enzymes were within normal range." (PMID 35012585, 2022). "Hypoalbuminemia is related to the development and severity of infectious illnesses, and robust innate and adaptive immune responses rely on albumin." (PMID 36233774, 2022). "Following stratification by the presence of hypoalbuminemia (<3 g/dL of serum albumin level), the difference in survival duration between the groups was significant (p < 0.001)." (PMID 36554049, 2022). "In critical illness, especially sepsis and severe trauma, vascular wall permeability increases, and trans-endothelial escape of serum albumin, the major oncotic plasma constituent, contributes to the development of hypoalbuminemia and edema formation." (PMID 36430652, 2022). "Albumin is the most abundant protein in the human serum, and hypoalbuminemia is a common manifestation among oncologic patients." (PMID 36449698, 2022). "Given the available methods to manage hypoalbuminaemia, interventional studies (such as exogenous albumin supplementation or nutritional status improvement of patients with AHF) are warranted." (PMID 35931952, 2022). "Further analysis found that probiotic supplementation also sharply increased serum total protein (57.87 ± 7.05 vs. 61.26 ± 6.69; P < 0.05) and albumin (32.21 ± 3.07 vs. 34.04 ± 3.56; P < 0.01) levels, and alleviated postoperative hypoalbuminemia." (PMID 36466862, 2022). "Further research is needed to delineate the role of albumin levels in patients treated with ICIs in the adjuvant setting, as well as the possible benefit of therapeutic approaches to improve hypoalbuminemia." (PMID 36533070, 2022). "Although serum albumin level of AN/BN patients is usually within the normal range, some cases show hypoalbuminemia." (PMID 38868660, 2022). "More than three-fourths (77.1%) of the study subjects were hypoalbuminemia (<3.4 mg/dl) with an average albumin level of 2.9 mg/dl (SD = 1.23)." (PMID 36420090, 2022). "Despite similar incidence of postoperative hypoalbuminemia (serum albumin less than 35 g/L) (50.4% vs. 45.7%, p = 0.12), the ERAS group had a lower incidence of severe postoperative hypoalbuminemia (serum albumin less than 30 g/L) (15.8% vs. 9.0%, p < 0.01)." (PMID 35331289, 2022).